IL6 (interleukin 6)
Diseases named in the same sentence as IL6 in open-access papers (continued):
Sharing a sentence is not in itself a finding about the gene and the disease.
colitis (continued). "DSS-induced colitis induces the massive infiltration of T and B lymphocytes, neutrophils, granulocytes, and macrophages, and they express various pro-inflammatory cytokines, including tumor necrosis factor (TNF)-α; interleukin (IL)-6, IL-8, IL-12, and IL-17; and IFN-γ." (PMID 32485960, 2020). "Severe colitis in HSD-fed mice was accompanied by a massive increase in neutrophils in colon tissue, increased anti-CD3/anti-CD28-stimulated production of IL-17 in mesenteric lymph nodes, and increased Tnfa expression and IL-6 and IL-1β production in the colonic tissue." (PMID 33339337, 2020). "The observed profile of cytokine modulation (IL-6/ TNF-α, IL-8) and inhibition of release of NO and 5-LOX may contribute to the in vivo effects demonstrated by indane dimers and PH46A in murine models of colitis." (PMID 32301120, 2020). "For example, TNFα, a critical driver of IEC shedding in colitis, induces superoxide generation via NOX2, NOX1 and the mitochondria, which will trigger, depending on the context, apoptosis, necroptosis, survival and further upregulation of proinflammatory cytokines such as TNFα and IL-6." (PMID 33059312, 2020). "In experimental colitis models, butyrate, a SCFA, produced by F. prausnitzii maintained Th17/Treg balance and exerted significant anti-inflammatory effects via inhibition of the IL-6/signal transducer, the STAT3/IL-17 pathway and promoted Foxp3 expression by targeting histone deacetylase 1 (HDAC1)." (PMID 32429359, 2020). "In addition, Mφs from the colon of Il10ra-deficient mice that spontaneously develop colitis exhibited elevated TLR-induced expression of Il23a, but not Il6 and Tnf." (PMID 30753547, 2019). "PXR activation by PCN is protective against DSS-induced colitis due to the activation of phase II enzymes and cellular efflux transporters, such as GSTa1, MDR1a, and MRP2, which alleviates the expression of the proinflammatory cytokines IL-6, TNF-α, ΜCP-1, and IL-1β." (PMID 30804707, 2019). "However, rosiglitazone may function through a PPARγ-independent pathway to suppress IL-6, TNF-α, and IL-1β production, as rosiglitazone administration attenuates colitis in IEC-specific PPARγ KO mice." (PMID 30804707, 2019). "Cytokines such as TNF-α and IL6 were highly expressed in humans with IBD and experimental models of IBD, and interventions to block their accumulation could protect against colitis." (PMID 31632373, 2019). "GH decreased the protein and mRNA levels of IL-6 and TNF-α, iNOS and COX-2 mRNA expression, the activation of NF-κB and MAPK pathways, the phosphorylation of AMPKα and PRAS40, histological damage, and infiltration of macrophages in the colons of mice with DSS-induced colitis." (PMID 32009962, 2019). "Moreover, it was previously reported that TNF-α, IL-6, and MCP-1 mRNA expression increased in mesenteric fat depots, 2 days after the induction of Trinitrobenzene Sulfonic Acid (TNBS)-Induced Colitis in mice, which could be dependent on the NF-κB pathway." (PMID 31211796, 2019). "A characteristic of DSS-induced colitis is the momentous infiltrates in the inflammatory lesions, composing mainly of T and B lymphocytes, macrophages, and neutrophils that produce a variety of proinflammatory cytokines such as TNF-α, IL-6, IL-8, IL-12, IL-17, and IFN-γ." (PMID 31780866, 2019). "Thus, the DSS-induced colitis resulted in an increase in MPO, INF-γ, IL6, IL1-β, TNF-α, and IL10." (PMID 28528363, 2018). "Importantly, cytokines including IL-6 and TNF-α are also increased in TNBS colitis, are known to alter colonic nerve function and may also contribute toward altered CMMC." (PMID 29933379, 2018). "The results showed that GW9662 itself did not affect the disease symptoms of mice with colitis, but significantly weakened bergenin-mediated regulation of levels of IL-6, TNF-α, acetylated NF-κB-p65, SIRT1 and nuclear translocation of NF-κB-p65 in colons, and consequent anti-colitis effect." (PMID 29375382, 2017).
colitis (continued). "Interestingly, after SPX, the treatment with α7 agonist lost completely its protective effects against colitis, being unable to lower IL-1β concentrations and exacerbating TNBS-induced increase of IL-6 levels, while leaving unmodified IFNγ and IL-10 colonic content with respect to SPX/C mice." (PMID 29167641, 2017). "Macroscopic and microscopic colitis in sedentary SD mice was accompanied by a significant fall in CBF, some increase in colonic tissue weight and a significant increase in the plasma levels of tumour necrosis factor-alpha (TNF-α), IL-6, monocyte chemotactic protein 1 (MCP-1) and IL-13 (p < 0.05)." (PMID 28425943, 2017). "In agreement with improved epithelial damage, GP supplementation reduced the protein and mRNA expression of both interleukin (IL)-6, and cyclooxygenase-2 (COX-2), and reduced the mRNA levels of IL-17, interferon (IFN-γ), and inducible nitric oxide synthase (iNOS) in the HFD-fed DSS-colitis mice." (PMID 28524086, 2017). "IL-6 also showed trend of increase in colitis, while TNF-α levels did not change." (PMID 28955126, 2017). "Likewise, treatment with fraxinellone, a natural lactone endowed with immunosuppressive activity, significantly reduced weight loss, diarrhea and colonic macroscopic damage, as well as myeloperoxidase, alkaline phosphatase, and colonic TNF, IL-1β, IL-6, and IL-18 levels in DSS-induced colitis mice." (PMID 28179906, 2017). "We showed that absence of FGF21 attenuates experimental colitis-induced adipose tissue lipolysis, and the effect may be mediated by IL-6 pathway." (PMID 28584524, 2017). "Elevated plasma levels of IL-6 seen in DSS colitis group was not reduced by MOS." (PMID 27658624, 2016). "However, IL-6 KO mice displayed more severe inflammation in a mouse model of DSS-colitis, which can be explained by the absence of the regenerative effects of IL-6 on intestinal epithelial cells." (PMID 27044016, 2016). "Finally, our data showed a strong relationship between overall tumor number and NF-κB/IL-6 positive cells at all examined time-points and indicated that NF-κB/IL-6 pathway may contribute to the transformation of CAC in this colitis mouse model." (PMID 25093140, 2014). "IL-6 production by sources other than IELs and at time points after the initial injury may explain our observation that blockade of IL-6 after colitis is induced in our spontaneous dnKO model did not result in improved disease." (PMID 25478789, 2014). "In this study, we have observed the high level of pro-inflammatory cytokines (IFN-γ, IL-6 and IL-17) produced by lymphocytes from spleen, MLN or colon of mice with DSS-induced colitis, further suggesting these pro-inflammatory cytokines are involved in the inflammation of colitis." (PMID 24788117, 2014). "In the mild colitis group, the expression of pro-inflammatory cytokines TNF-α, IL-6, IL-1β were increased to about 1.5 folds (p<0.05), and in the severe colitis group IL-6, TNF-α, IL-1β expression were increased to about 3, 2, and 1.5 folds compared to the water group." (PMID 24504372, 2014). "In this study, the DAI and HI scores, MPO activity in colonic tissues, as well as the MDA, TNF-α, IL-1β, and IL-6 levels, were simultaneously increased in TNBS-induced colitis rats with Hcy injection, indicating that Hcy can aggravate the oxidative and inflammatory damage in rats with colitis." (PMID 24787389, 2014). "Given that activated neutrophils, monocytes and macrophages up-regulated the production of pro-inflammatory mediators such as TNF-α and IL-6 in experimental colitis, we further investigated whether chronic VNS could decrease the levels and expression of TNF-α and IL-6." (PMID 23936328, 2013). "Indeed, we found that in the IL-10−/− mice there was an overproduction of IFN-γ and IL-17, whereas in DSS-induced model of colitis occurred a prevalence of IL-6, TNF-α, and INF-γ without alterations in IL-17 production (data not shown)." (PMID 22400037, 2012).
colitis (continued). "THSG appears to exert its beneficial effects on acetic acid-induced experimental colitis through upregulation of PPAR-γ mRNA and protein levels and inhibition of the NF-κB pathway, which in turn decreases the protein overexpression of the downstream inflammatory mediators TNF-α, IL-6 and COX-2." (PMID 21993246, 2011). "The development of colitis in the Gαi2−/− mouse model is dependent on the presence of an enteric microflora (unpublished observations) and is characterized by a Th1 CD4+ T cell response, with increased production of IFN-γ, together with increased levels of IL-1, IL-6 and TNF-α in inflamed tissue." (PMID 21966415, 2011). "In contrast, pre-treatment with Bb-CM by i.p. route induced a significant protection against colitis (WS = 1.7±0.8, 62% protection) and a statistically significant decrease in pro-inflammatory cytokine expression [IL-1β, CXCL1 (equivalent to human IL-8), COX2, IL-23, IL-6]." (PMID 19381276, 2009). "Therefore, our data provide new hints for an immune-regulating rather than immune-activating role of IL-6 in the colitis model of IL-2−/−-mice suggesting that IL-6 in the absence of TNF-α, IL-12 and IFN-γ exerts anti-inflammatory effects." (PMID 18545662, 2008). "The combination of Radix Astragali polysaccharides with CP polysaccharides in a mouse model of colitis could improve colitis symptoms in mice by elevating SOD, decreasing MDA to improve antioxidant activity, and simultaneously decreasing the expression of inflammatory factors TNF-α, IL-1β, and IL-6." (PMID 38803438, 2024). "In addition, one study also found that fermented wild ginseng could relieve the symptoms of colitis in a DSS-induced colitis animal model through inhabiting secretion level of proinflammatory cytokines (IL-1β, IL-6, IL-12, p40, TNF-α, and IFN-γ) and blocking NF-κB signaling pathway." (PMID 38698858, 2024). "Enhanced colonic IL-6 was also seen in models of mice challenged with acute infection with Citrobacter rodentium or Dextran Sulfate Sodium (DSS) followed by anti-CTLA-4 administration, suggesting that IL-6 may serve as a cytokine signature in ICI-induced colitis." (PMID 39247203, 2024). "Furthermore, IL-6 and GSP were associated with MES in extensive colitis but not in distal colitis." (PMID 37457023, 2023). "Taken together, these results suggest that Se-SDF could inhibit the pathogenesis of colitis in mice by promoting the release of anti-inflammatory cytokines (IL-10 in male and female mice) and suppressing pro-inflammatory cytokines (TNF-α and IL-6 in female mice, TNF-α in male mice)." (PMID 36159466, 2022). "Consequently, we found PYY 3–36 had a protective role in mice with TNBS-induced colitis and this protection might be through inhibiting the production of proinflammatory cytokines TNF-α and IL-6 from activated macrophages and by modulation of the balance of Th1/Th2." (PMID 35443853, 2022). "Therefore, to examine whether MLN DCs from Yeti/CD1d KO mice show proinflammatory phenotypes during DSS-induced colitis, we compared proinflammatory cytokine production (i.e., IL12, TNFα, and IL6) by both splenic DCs and MLN DCs from WT, Yeti, CD1d KO, and Yeti/CD1d KO mice during DSS treatment." (PMID 36499642, 2022). "Interestingly, HIF-2α deletion in a mouse model of moderate DSS-induced colitis was shown to be protective, whereas genetic HIF-2α overexpression in intestinal epithelial cells resulted in spontaneous DSS colitis via increased expression of TNF-α, IL-1β, and IL-6." (PMID 34571989, 2021). "Therefore, tissue‐prevalent mast cells stimulated by a combination of IL‐3 and IL‐33 would secrete high levels of IL‐6, but not IL‐2, and represent potential mediators of the negative regulatory role of IL‐3 in colitis‐mediated immune responses by induction of RORγt+ Tregs." (PMID 33427298, 2021).
colitis (continued). "Moreover, MSC-derived exosomes alleviate colitis in vivo by inhibiting expression of IL-7 and inducible nitric oxide synthase (iNOS) in mouse colonic macrophages, thus limiting the production of nitric oxide and the expression of TNF-α, IL-6 and IL-1β and increasing IL-10 secretion." (PMID 32365813, 2020). "Furthermore, the serum TNF-α, IFN-γ, IL-1β, IL-6, and IL17 were significantly increased in the colitic mice, and hMSCs treatment could reduce these inflammatory cytokines, suggesting that hMSCs alleviated the inflammatory responses in colitis mice." (PMID 31367246, 2019). "Indeed, we found increased levels of pro-inflammatory cytokines IL-6, MCP-1, and TNF-alpha in colonic tissue of colitic mice and a normalization effect of EGCG on these cytokines, in resonance with results from previous studies of EGCG using different colitis models." (PMID 31362373, 2019). "Indeed, GSK343 administration led to a profound decrease in the levels of pro-inflammatory cytokines, including IL-6 and IL-1β, whereas the levels of TNF-α and IL-17A remained unaffected, indicating that GSK343 treatment reduces the inflammatory response during DSS-induced colitis." (PMID 31160593, 2019). "However, mast cell reconstitution did not reduce the elevated IL6 or IL12p40, indicating that mast cells may be specifically regulating specific cytokines and (or) proinflammatory mediators to dampen colitis." (PMID 29849494, 2018). "Thus, IL-6/STAT-3 signaling could contribute to FOLFIRI-related mucosal damage by controlling the proliferation and survival of intestinal epithelial cells as observed in colitis." (PMID 29706892, 2018). "Thus, we examined whether EBN reduces IL-6, MCP-1, and COX-2 levels in DSS-induced colitis mice." (PMID 25045208, 2014). "Additionally, studies in genetically engineered mice have demonstrated that epithelial STAT3 activation in dextran sodium sulfate colitis is dependent upon IL-22 rather than IL-6, and that both IL-22 and epithelial STAT3 is important in wound-healing experiments in vivo." (PMID 23379788, 2013). "In addition, neither Il6 nor Ifng could be detected in the control samples but both were measured in the colitis groups." (PMID 18928539, 2008). "A decrease in intestinal macrophage and Th2 lymphocyte activity (decrease in IL-1β, IL-6, and IL-10 levels) was observed in the intestines induced by DSS in non-acute colitis (equivalent to non-acute UC), which was enhanced by SST-14 and OCT administration." (PMID 40508145, 2025). "This subset has previously been observed in the mucosa of children with colitis, where CD8+ T cells can differentiate into non-classic Tc2 cells under stimulation with TGF-β in combination with IL-1β/TNF-α or IL-6, thus contributing to the disease." (PMID 40244207, 2025). "It did not affect the transcription of TNF, IL-6, and IL-10, suggesting that additional proinflammatory cues, as provided during DSS colitis, are required to induce TNF upregulation." (PMID 36413219, 2023). "In the initiation phase of colitis, IL-6 upregulation is independent of CCN1, but later in the repair phase (8 days after DSS administration), IL-6 overexpression is mainly CCN1-dependent." (PMID 38106420, 2023). "In PTENΔDC mice, we found elevated IL-6 serum levels, but no changes in IL-33 or CXCL-1 (also known as KC), which previously have been shown to be increased during colitis." (PMID 35514976, 2022). "In female C57BL/6 mice, nicotine (0.25 and 2.50 μmol/kg, i.p.)treatment reduced the activation of NF-κB and colonic cytokine production, including IL-6, IL-17, and TNF, but failed to reduce the disease parameters in DSS colitis." (PMID 35251010, 2022). "The results showed that the mRNA expression levels of Cgas, Il10, Cxcl10, Ifnb1, Tnf, Il6, and Il1b exhibited no obvious difference between GCV and vehicle treatment groups in DSS-colitis in STINGgt/gt mice (all p > 0.05)." (PMID 36467059, 2022).
colitis (continued). "Our results suggest that chemogenetic inhibition of TRPV1+ neurons is not sufficient to reduce DSS-induced colitis, whereas CNO stimulation induces neurogenic inflammation in the colon, highlighted by TNF-α, IL-1β, or IL-6 upregulation." (PMID 34954381, 2022). "Increased expression of pro-inflammatory cytokines, Il-1β, Il-6, and TNF-α, monocyte chemotactic protein-1 (Mcp-1) and macrophage inflammatory protein 2 (Mip-2), characterized DSS-induced colonic inflammation compared to non-colitic mice." (PMID 34072532, 2021). "A patient with colitis grade 3, who did not respond to either steroids or anti-TNF-α, was treated with anti-IL6, with event resolution." (PMID 34208218, 2021). "Compared to patients with no colitis, Ipilimumab-induced baseline CD4(+) T cell levels are significantly increased, and several inflammatory biomarkers (IL-6, IL-8, and SCD25) are significantly reduced." (PMID 34485534, 2021). "Although previous studies in the DSS-induced colitis mouse model demonstrated anti-inflammatory effects of IMD with reduction of TNF-α and IL-6, we did not see any effect on these cytokines." (PMID 32679670, 2020). "RA treatment significantly decreased the levels of TNF-α, IL-6, and IL-1β in colon tissue in WT mice during DSS-induced colitis, but the effect is not obvious in LXN−/− mice." (PMID 32555320, 2020). "Second, many genes differentially expressed between TWD and AIN diets at colitis were still upregulated at the recovery time point compared to pre-DSS, though not markedly more so in TWD-fed mice (e.g., Ifna1, Il6, Tnf)." (PMID 32093192, 2020). "Soy oligosaccharides have been previously reported to inhibit colitis in a mouse model, as well as to suppress the expression of inflammatory biomarkers, including COX-2, CSF-1, and IL-6, without affecting the NF-κB expression level." (PMID 32708415, 2020). "The levels of IL-6, IL-17A, IL-23, TNF-α, and TGF-β1 in the colonic mucosa of colitis mice without treatment were higher than in the DSS + SSP and DSS + 5-ASA groups." (PMID 32581849, 2020). "In these mice, lack of KNG1 reduced colitis development, infiltration of inflammatory cells into the gut mucosa, and inflammatory cytokine levels (e.g., TNFα, IFN-γ, IL-1β, and IL-6)." (PMID 31623319, 2019). "Levels of pro-inflammatory cytokines IL-6, IL-8, and TNF-α were all increased extremely significantly in colitis group compared with the negative control (CON)." (PMID 31726738, 2019). "A further significant increase in the expression of TNF-α, IL-6 and MCP-1 mRNA was recorded in the mice with colitis fed a HFD as compared to the sedentary mice without colitis fed a HFD (p < 0.05)." (PMID 28425943, 2017). "The levels of IFN-γ, TNF-γ, IL-1β, IL-12p70 and IL-6, but not IL-10, were significantly higher in IL-21RKO mice than those in C57BL/6 mice on day 5 after DSS-induced colitis (*P < 0.05)." (PMID 27545302, 2016). "Lack of elevated IL-6 and TNFα in the colon of AOM/DSS treated mice indicates that the mucosa is almost completely recovered from colitis during 2-week recovery period." (PMID 26951793, 2016). "Sodium butyrate ameliorated histological colitis and decreased levels of tumor necrosis factor (TNF)-α and IL-6 in IL-10−/− mice compared with those without treatment." (PMID 27886121, 2016). "The results show that MMF significantly inhibited mRNA expression of pro-inflammatory cytokines IFN-γ, TNF-α, IL-12, IL-6, and IL-1β in mice with TNBS-induced colitis; however, MMF did not inhibit the expression of IL-10 mRNA." (PMID 26561804, 2015). "Other cytokines (TNF-α, IL-1β, IL-6, IL-23, and IL-12p70) were detected in low levels and were not significantly different between the rIL-33- and PBS-treated mice with DSS colitis (data not shown)." (PMID 26161006, 2015). "Compared to WT colitis mice, lack of TNF-R1 resulted in significant up-regulation of IL-6, IL-1β, MCP-1, IL-17A levels in the colon tissues." (PMID 23285227, 2012).